WDFY4 (WDFY family member 4)
Diseases named in the same sentence as WDFY4 in open-access papers:
WDFY4 is named in the same sentence as 29 diseases in open-access papers, as found by Europe PMC text mining. Sharing a sentence is not in itself a finding about the gene and the disease. The quoted sentences say what the papers report.
systemic lupus erythematosus (11 papers, 2010 to 2024). An autoimmune multi-organ disease typically associated with vasculopathy and autoantibody production. "We also detected increased DNA methylation after MTX treatment in CD4+ memory T cells at a CpG located in the WDFY4 gene, which is a gene reported to harbour SNPs associated with several rheumatic diseases, i.e. systemic lupus erythematosus, JIA and RA." (PMID 34867944, 2021). "Genetic variants in and around the WDFY4 gene were identified as associated with systemic lupus erythematosus and with severe tick-borne encephalitis." (PMID 34178030, 2021). "Wdfy4 regulates B cells through atypical autophagy and is genetically related to the susceptibility of systemic lupus erythematosus (SLE) of various races." (PMID 33679872, 2020). "A milder pristane-induced lupus phenotype was also observed in Wdfy4-CKO mice, including lower anti-dsDNA IgG, reduced immune complex deposition and inflammation in the kidney, and fewer spontaneous germinal centers in the spleen." (PMID 38507703, 2024). "Several studies have demonstrated a correlation between WDFY4 and certain autoimmune diseases, such as systemic lupus erythematosus, rheumatoid arthritis, juvenile idiopathic arthritis and clinical anaplastic dermatomyositis." (PMID 37728413, 2023). "E26 transformation-specific-1 (ETS1) and WDFY family member 4 (WDFY4) are closely related with systemic lupus erythematosus." (PMID 24549174, 2014). "Previous studies have shown that WDFY4 is involved in the function of various immune cells, and it can modulate B cells through noncanonical autophagy, and participates in the regulation of systemic lupus erythematosus." (PMID 37670814, 2023). "In addition, we also found that FNLS-YE1 could efficiently introduce protective alleles in TYK2 /WDFY4 and PCSK9/ANGPTL4, offering a potential approach to reduce susceptivity for systemic lupus erythematosus (SLE) and familial hypercholesterolemia (FH), respectively." (PMID 37285261, 2023).
autoimmune disease (5 papers, 2015 to 2025). A disorder resulting from loss of function or tissue destruction of an organ or multiple organs, arising from humoral or cellular immune responses of the individual to their own tissue constituents. "WDFY4 is implicated as a susceptibility locus in autoimmune disorders such as systemic lupus erythematosus, rheumatoid arthritis and clinically amyopathic dermatomyositis." (PMID 40755163, 2025). "WD repeat and FYVE domain‐containing 4 (WDFY4), a susceptibility gene for autoimmune diseases and reported AS hub gene, is associated with ferroptosis and inflammation." (PMID 40755163, 2025). "Functional annotation and expression studies have identified candidate causal variants, supporting a role for WDFY4 in autoimmune disease risk." (PMID 38507703, 2024). "In this review, we will discuss the WDFY4 gene structure, functional roles, and association with autoimmune diseases, including myositis." (PMID 38507703, 2024). "GWAS identified and confirmed the association of multiple WDFY4 variants in different ancestry populations with autoimmune diseases, especially SLE, RA, and PBC." (PMID 38507703, 2024). "Meanwhile, there is insufficient evidence to establish an association between WDFY4 and specific clinical phenotypes of other autoimmune diseases, such as SLE or RA-related ILD." (PMID 38507703, 2024). "WDFY4 variants are also associated with other autoimmune diseases, including RA and primary biliary cholangitis (PBC), in different ancestry cohorts." (PMID 38507703, 2024). "Here, we briefly review the association of WDFY4 with autoimmune diseases and its known function in the immune response." (PMID 38507703, 2024). "WDFY4, a large protein of unknown function primarily expressed in immune tissues, has been reported that WDFY4 is a susceptibility gene for a variety of autoimmune diseases, such as lupus erythematosus, primary biliary cholangitis, idiopathic arthritis and type 1 diabetes." (PMID 40755163, 2025). "The overall survival rate is longer in melanoma patients with high WDFY4 expression, which is highly correlated with the progression of cancer and autoimmune disorders." (PMID 37728413, 2023). "Further studies are required to validate the role of WDFY4 in autoimmune diseases." (PMID 38507703, 2024). "Based on the large GWAS conducted across multiple autoimmune disease cohorts and recent findings from functional experiments, our understanding of the role of WDFY4 in the anti-viral and anti-tumour immune responses has markedly advanced in the past five years." (PMID 38507703, 2024). "Also, the functions of WDFY4 and its role in the pathogenesis of autoimmune diseases haven’t been fully illustrated." (PMID 38507703, 2024).
amyopathic dermatomyositis (4 papers, 2019 to 2025). "It has been clinically found to be significantly associated with Wdfy4 and patients with myopathy dermatomyositis." (PMID 33679872, 2020). "A genome-wide association study conducted in the Japanese population identified a significant association with WDFY4 in patients with clinically amyopathic dermatomyositis." (PMID 31415030, 2019).
rheumatoid arthritis (3 papers, 2014 to 2023). A chronic, systemic autoimmune disorder characterized by inflammation in the synovial membranes and articular surfaces. "We hypothesized that ETS1 and WDFY4 polymorphisms may contribute to rheumatoid arthritis (RA) susceptibility." (PMID 24549174, 2014).
melanoma (2 papers, 2020 to 2023). A malignant, usually aggressive tumor composed of atypical, neoplastic melanocytes. "Melanoma patients with high expressions of Wdfy4, Parp14, Cybb, Itgb2, and Itgam were found to be associated with the longer OS time in melanoma." (PMID 33679872, 2020). "The PPI network analysis revealed that 6 hub genes, comprising Itgb2, Wdfy4, Itgam, Cybb, Mmp2, and Parp14, might be key candidate genes related to the pathogenesis of melanoma." (PMID 33679872, 2020). "The DFS time analysis revealed that there was a similar trend that high expressions of Wdfy4, Parp14, Cybb, Itgb2, and Itgam were correlated to longer DFS time in melanoma." (PMID 33679872, 2020). "Based on the TCGA database, we found that Wdfy4, CYBB, Itgb2, and Itgam were down-regulated and MMP2 was up-regulated in melanoma samples compared with normal samples." (PMID 33679872, 2020).
primary biliary cholangitis (2 papers, 2024 to 2025). Primary biliary cholangitis (PBC) is a chronic and slowly progressive cholestatic liver disease of autoimmune etiology characterized by injury of the intrahepatic bile ducts that may eventually lead to liver failure. "WDFY4 variants are also associated with RA and primary biliary cholangitis, in different ancestry populations." (PMID 38507703, 2024).
atherosclerosis (1 paper, 2025). A disease characterized by the build-up of fatty material and calcium deposition in the arterial wall resulting in partial or complete occlusion of the arterial lumen. "In this study, we focus on the atherosclerosis‐associated hub gene WDFY4 to investigate its functional role in AS pathogenesis." (PMID 40755163, 2025). "Bioinformatic analyses indicate WDFY4 upregulation in atherosclerosis samples compared to healthy controls, designating it as a hub gene in AS pathogenesis." (PMID 40755163, 2025). "This study explored the mechanism of WDFY4 affecting atherosclerosis." (PMID 40755163, 2025). "Finally, mice with endothelial‐specific WDFY4 knockout were protected against atherosclerosis." (PMID 40755163, 2025). "However, the mechanism by which WDFY4 affects atherosclerosis remains unclear." (PMID 40755163, 2025).
autism spectrum disorder (1 paper, 2024). A spectrum of developmental disorders that includes autism, and Asperger syndrome. "WDFY4 gene is regarded as a strong candidate autism spectrum disorder (ASD) gene." (PMID 38784233, 2024).
Chediak-Higashi syndrome (1 paper, 2024). ChC)diak-Higashi syndrome (CHS) is a rare severe genetic disorder generally characterized by partial oculocutaneous albinism (OCA), severe immunodeficiency, mild bleeding, neurological dysfunction and lymphoproliferative disorder. "WDFY4 is a member of the BEACH (Beige and Chediak-Higashi) domain-containing family, named after a rare and lethal autosomal recessive disorder, Chediak-Higashi syndrome (CHS), and its animal model Beigej mouse." (PMID 38507703, 2024).
Granuloma (1 paper, 2025). A compact, organized collection of mature mononuclear phagocytes, which may be but is not necessarily accompanied by accessory features such as necrosis. "A diverse array of innate immune cells, including mast cells (MC) (cluster 20: HDC, CPA3, KIT), dendritic cells (DC) (cluster 23: CLNK, WDFY4, FLT3), neutrophils (FCGR3B, FFAR2, CSF3R), and macrophages (CD68, CD163, C1QA/B/C), was also present in these granulomas." (PMID 40772762, 2025).
Hypertension (1 paper, 2024). The presence of chronic increased pressure in the systemic arterial system. "Numerous studies have suggested that the WDFY4 gene plays a significant role in kidney dysfunction development as well as hypertension, which is a common risk factor for kidney dysfunction, and exerts a significant effect on kidney function and immune response." (PMID 39143076, 2024).
lentivirus infection (1 paper, 2023). Virus diseases caused by the Lentivirus genus. "To investigate the potential influence of WDFY4 on the progression of lung cancer in vivo, we subcutaneously injected A549 cells that were stably expressing WDFY4 following lentivirus infection into nude mice." (PMID 37728413, 2023).
lung adenocarcinoma (1 paper, 2023). A carcinoma that arises from the lung and is characterized by the presence of malignant glandular epithelial cells. "To investigate the biological effect of WDFY4 on lung adenocarcinoma cells, we employed the lung adenocarcinoma A549 cell line and used lentivirus to transfect A549 cells to establish a WDFY4 overexpression cell model." (PMID 37728413, 2023). "Overexpression of WDFY4 has shown to inhibit the growth of lung adenocarcinoma A549 cells both in vitro and in vivo." (PMID 37728413, 2023). "Furthermore, the overexpression of WDFY4 can significantly inhibit the growth of lung adenocarcinoma in vitro and in vivo, highlighting its potential as a target for immunotherapy in LUAD." (PMID 37728413, 2023). "Simultaneously, we employed lentivirus transfection as a means to establish a cell model with overexpressed WDFY4, and found that the overexpression of WDFY4 could inhibit the growth of lung adenocarcinoma A549 cells both in vitro and in vivo." (PMID 37728413, 2023). "The data presented herein indicate that the upregulation of WDFY4 exerts a substantial inhibitory effect on the proliferation of lung adenocarcinoma cells both in vitro and in vivo, thereby highlighting its potential as a viable therapeutic target for the treatment of lung adenocarcinoma." (PMID 37728413, 2023).
lung carcinoma (1 paper, 2023). "To conduct a more comprehensive examination of the expression of WDFY4 in LUAD tissues and its relationship with the prognosis of lung cancer patients, we analyzed the expression of WDFY4 in LUAD tissue microarray through immunohistochemistry (IHC)." (PMID 37728413, 2023). "Correlation of the expression of WDFY4 in lung cancer with clinicopathologic features." (PMID 37728413, 2023). "Thirdly, a comprehensive examination should be undertaken to evaluate the differentiation and infiltration of B cells by expressing or knocking down WDFY4, with the ultimate aim of exploring the potential mechanism of WDFY4 as targeted immunotherapy in lung cancer by regulating B cells." (PMID 37728413, 2023). "The results indicated that WDFY4 was notably reduced in LUAD tissues, and the patients with low WDFY4 expression exhibited a worse prognosis, particularly in relation to the primary sites of lung cancer." (PMID 37728413, 2023).
lupus erythematosus (1 paper, 2025). An autoimmune, connective tissue chronic inflammatory disorder affecting the skin, joints, kidneys, lungs, heart, and the peripheral blood cells. "It has also been found that WDFY4 deficiency in mice with lupus erythematosus was effectively alleviated." (PMID 40755163, 2025).
prostate carcinoma (1 paper, 2025). A carcinoma that arises from epithelial cells of the prostate gland. "Genes such as ASCL1, WDFY4, GLYATL2, and EDIL3, which are upregulated in CRPC, likely drive the progression from primary prostate cancer to CRPC." (PMID 40165961, 2025).
sarcoma (1 paper, 2022). A usually aggressive malignant neoplasm of the soft tissue or bone. "Wdfy4−/− cDC1s failed to cross-present cell-associated antigens in vitro, and importantly, Wdfy4−/− mice failed to reject immunogenic sarcomas." (PMID 34480145, 2022).
viral infection (1 paper, 2023). "These include genes encoding for WDFY4, which is essential for cross-presentation of cell-associated antigens by cDC1 via the cytosolic pathway and PPT1, which protects XCR1+ cDCs from viral infection by promoting antigen degradation and endosomal acidification." (PMID 37954617, 2023).
tumor (18 papers, 2017 to 2025). "cDC1s express a range of proteins that have been shown to be involved in the cross‐presentation of cellular antigens, such as DNGR‐1 (a.k.a CLEC9A) and WDFY4, both of which are crucial for anti‐tumour immunity in murine tumour models." (PMID 40745918, 2025). "Functional studies in recent years have confirmed that WDFY4 plays a role in anti-infection and anti-tumour immunity through cross-presentation." (PMID 38507703, 2024). "Recent findings have indicated that WDFY4 plays a crucial role in regulating cDC1-mediated cross-presentation of viral and tumor antigens." (PMID 37728413, 2023). "Another identified interactor of RFLNB/FAM101B was WDFY4, which plays a critical role in the regulation of classical dendritic cells mediated cross-presentation of viral and tumor antigens." (PMID 37798266, 2023). "Further, the critical role of the BDCP WDFY4 in tumor rejection illustrates the variability of cells in processing antigens and the importance of using model systems that reflect the in vivo situation." (PMID 34480145, 2022). "MKI67 expression is associated with a higher tumour grade and early disease recurrence, and WDFY4 plays a critical role in the regulation of certain viral and tumour antigens in dendritic cells." (PMID 35653351, 2022). "WDFY4 was reported to be essential for the cross-presentation of tumor-derived antigens and for antiviral and antitumor immunity." (PMID 36216827, 2022). "The demonstration of a cell-intrinsic requirement of WDFY4 in cDC1 for immunity against cancer was achieved by comparing tumor growth between Wdfy4−/−:WT vs. Wdfy4−/−:Batf3−/− mixed bone marrow chimera mice." (PMID 30809220, 2019). "Although the cellular mechanism for WDFY4 activity remains unknown, this study revealed that WDFY4 is essential in anti-viral and anti-tumour immunity." (PMID 38507703, 2024). "Highlighting the importance of this pathway in tumor immunity is the loss of WDFY4, a BEACH-domain containing protein essential for cross-presentation in conventional DCs, which results in failure to both prime CD8 T cells and reject tumor in preclinical models." (PMID 38903502, 2024). "The most downregulated genes contained known tumor suppressors (ZNF831, AKNA, NR4A1, ARHGAP9, ZBTB16) and regulators of immune response (NLRC5, WDFY4, RASGRP2, IKZF1)." (PMID 39794830, 2025). "Additional Fc1(a) solo-LTR insertions within genes include, but are not limited to, homologs involved in tumor suppression (EXT1) and immune functions (WDFY4)." (PMID 38055724, 2023). "In Pr4, we identified 10 mutations that were not present in the other primary tumour regions, of which three (in BLOC1S4, WDFY4, and CUBN) were shared with VT and all lung metastases." (PMID 31212796, 2019). "Furthermore, deletion of WDFY4, a vesicular trafficking gene required for cross-presentation by cDC1s, but not moDCs, abrogated tumor rejection." (PMID 38903502, 2024). "Importantly, mice lacking Wdfy4 were unable to suppress tumor growth." (PMID 36479127, 2022). "Wdfy4 −/− mice failed to prime virus-specific CD8+ T cells in vivo or induce tumor rejection, revealing a critical role for cross-presentation in anti-viral and anti-tumor immunity." (PMID 36739406, 2023).
cancer (6 papers, 2019 to 2025). A tumor composed of atypical neoplastic, often pleomorphic cells that invade other tissues. "WDFY4, found to be up-regulated both in TCGA- and GEO-LGG samples, is implicated in autophagy and also the processing and cross-presentation of viral and cancer antigens by dendritic cells." (PMID 36945359, 2023). "As a result, our study suggests that it might be a novel strategy for LUAD immunotherapy to promote cancer infiltration and activation of B cells by inducing ferroptosis in cancer cells and elevating WDFY4 expression." (PMID 37728413, 2023). "Besides, the promotion of cancer cell ferroptosis and upregulation of WDFY4 expression have been shown to induce the infiltration and activation of B cell populations." (PMID 37728413, 2023). "It was also confirmed that WDFY4 could inhibit cancer growth in vivo." (PMID 37728413, 2023). "Compared to primary cancer samples, genes such as GLYATL2, EDIL3, MEG3, FABP4, ASCL1, GRP, and WDFY4 were highly upregulated in CRPC, with statistically significant differences underscoring their potential roles in driving the castration-resistant phenotype." (PMID 40165961, 2025).
WDFY4 also shares sentences with these, for which no sentence is quoted: fibrosarcoma (1 paper); infection (1); interstitial lung disease (1); juvenile idiopathic arthritis (1); myopathy (1); non-small cell lung carcinoma (1); rheumatic diseases (1); tick-borne encephalitis (1); type 1 diabetes (1).